HSP90AB1 (heat shock protein 90 alpha family class B member 1)
Diseases named in the same sentence as HSP90AB1 in open-access papers (continued):
Sharing a sentence is not in itself a finding about the gene and the disease.
tumor (continued). "Additionally, the heat shock protein family genes (HSPD1, HSPA1B, and HSP90AB1) facilitate tumor growth and invasion via intricate intracellular signaling networks." (PMID 37533434, 2023). "The secretome was enriched with atypical tumor suppressors such as Hsp90ab1 and moesin (MSN)." (PMID 34976221, 2022). "Furthermore, extracellular Hsp90ab1 was enriched in the proteome, and it induced anti-tumor, anti-inflammatory actions via the GAPDH-L1CAM regulatory axis." (PMID 35804814, 2022). "Notably, the inhibitory effect of Lrp5- and Akt-overexpressing MSC CMs, Hsp90ab1 and Calr presented selective inhibition to tumor cells than non-tumor cells." (PMID 33859739, 2021). "BM CM was enriched with atypical tumor-suppressing proteins such as Hsp90ab1 and enolase 1 (Eno1)." (PMID 34830748, 2021). "In combination with prior findings, our data supported the hypothesis that Hsp90ab1 plays an important role in tumorigenesis in multiple tumor types." (PMID 30305727, 2019). "Thus, we further examined Hsp90ab1-mediated anti-tumor, anti-inflammatory actions." (PMID 35804814, 2022). "HSP90AB1 may also regulate angiogenesis, an important function in tumour progression." (PMID 30138346, 2018). "All three upregulated genes showed significantly increased expression in tumor tissues, with fold changes of 4.2 (RFC2, p=0.007), 3.7 (HSP90AB1, p=0.011), and 3.4 (YWHAZ, p=0.015), respectively." (PMID 41164201, 2025). "Blocking Hsp90ab1 with geldanamycin prevents UPR-induced activation and EMT, pointing to the UPR-Hsp90ab1 axis as a driver of tumor cell reprogramming." (PMID 41228282, 2025). "Whereas JUN, HSPH1, HSPA8, HSPA6, HSP90AB1, and EGR1 were found to be the DEGs in both Tumor vs. normal and tumor vs. metastasis group." (PMID 37335089, 2023). "Generally, heat shock protein family genes (HSPD1, HSPA1B, HSP90AB1, and HSPH1) enhance tumor growth and invasion through complex intracellular signaling networks." (PMID 37533434, 2023). "Then, we analyzed the relapse-free survival rate (RFS) of abnormal expression of ATP6AP1, PSMD14 and HSP90AB1 in these 63 HCC tissues and paired non-tumor tissues through five years of follow-up and in the K-M plotter database." (PMID 38327651, 2023). "According to the results, ATP6AP1, PSMD14 and HSP90AB1, which are generally highly expressed in HCC tissue, were chosen and verified the expressions in 63 cases of HCC tissues and the paired adjacent non-tumor tissues." (PMID 38327651, 2023). "In this study, we validated the high expression of ATP6AP1, PSMD14 and HSP90AB1 in HCC tissue and the aberrant expression of PSMD14 in tumor tissue related to the poor prognosis." (PMID 38327651, 2023). "Among them, the actions of 6 tumor-suppressing proteins, ENO1, Ubiquitin C (UBC), Moesin (MSN), heat shock protein 90ab1 (HSP90ab1, aka HSP90β), Calreticulin (CALR), and Histone H4 (H4), have been documented with a proposed mechanism 12-14." (PMID 37056934, 2023). "The result showed that the inhibitory effect of Lrp5 CM, Hsp90ab1, and MSN was largely selective to tumor cells than non-tumor cells." (PMID 34976221, 2022). "The role of Hsp90ab1 and GAPDH differed in their locations and they acted as the uncommon protectors of the joint tissue from tumor and inflammatory responses." (PMID 35804814, 2022). "While Lrp5 CM, mostly analyzed in this study, contains a spectrum of secretomes, we focused on the role of three moonlighting proteins, OPN, Hsp90ab1, and MSN, for tumor suppression." (PMID 34976221, 2022). "The individual and combined efficacies of Hsp90ab1 and Eno1 recombinant proteins were plotted in the concentration range of 1 ng/mL to 5 μg/mL, showing their additive anti-tumor effects on MTT-based tumor viability." (PMID 35547745, 2022). "Hsp90ab1 and MSN are atypical tumor-suppressing proteins since they are multi-tasking, moonlighting proteins that promote tumorigenesis in tumor cells." (PMID 34976221, 2022).
tumor (continued). "We next examined the mechanism of the action of OPN by focusing on Hsp90ab1 and MSN, two atypical tumor-suppressing proteins." (PMID 34976221, 2022). "Consistently, a tumor-suppressive cytokine, IL27, was elevated in BM CM, while its level was reduced in Hsp90ab1 siRNA-treated osteoclast-derived CM." (PMID 34830748, 2021). "In comparison, HSP90B1 (GP96), HSP90AB1 and HSPD1 (HSP60) were expressed at significantly higher levels in tumour cell lines than skin." (PMID 29702669, 2018). "Three members of the HSP90 gene family (HSP90AA1, HSP90AB1, and HSP90B1) analyzed were all down-regulated following OCT4B1 suppression in all three tumor cell lines except for HSP90B1 in AGS cells that showed less than 2-fold up-regulation." (PMID 26862520, 2016). "Some molecules that play important roles in tumor development signaling pathways such as epidermal growth factor receptor (EGFR), human epidermal growth factor receptor-2 (HER2) are Hsp90AB1 client proteins." (PMID 26903158, 2016). "Finally, ATP6AP1, PSMD14 and HSP90AB1 were chosen to validate the expressions in 63 cases of HCC tissues and the corresponding adjacent non-tumor tissues." (PMID 38327651, 2023). "We found that only ATP6AP1, PSMD14 and HSP90AB1, were generally existent and highly expressed in tumor tissue (data not shown)." (PMID 38327651, 2023). "While Hsp90ab1 may assist the stability of GAPDH as a molecular chaperon, we observed that they both served as tumor suppressors to CS cells." (PMID 35804814, 2022). "The expression levels of CCND1, VEGFA, AURKB, HDAC1, HSP90AA1, and HSP90AB1 were positively correlated with immune cell infiltration levels, whereas the expression levels of SIRT2 and CASP9 were negatively correlated with the tumor purity of BRCA." (PMID 35845599, 2022). "Further investigation of the regulatory mechanism may provide better insight into the precise roles of Hsp90ab1, MSN, CD44, and FN1 in the anti-tumor action of Lrp5 CM." (PMID 34976221, 2022). "The C allele of rs2282151 was associated with increased mRNA expression level of HSP90AB1, which expressed higher in CRC tumor tissues than paired normal tissues." (PMID 27756247, 2016). "The differential interactome composition indicates a functional shift in EGFR signaling that may drive increased tumor cell adhesion (CD44, ITGB1, FN1), metabolic adaptation (GAPDH, ENO1) and stress response (HSPA4, HSP90AB1), consistent with mechanisms observed in therapy‐resistant CRC phenotypes." (PMID 41319168, 2025). "In addition to the recombinant Eno1 proteins, the partial silencing of CD44 in EO771 tumor cells reduced the inhibitory effect of recombinant Hsp90ab1 proteins on MTT-based viability, and partially suppressed the Hsp90ab1-driven downregulation of Lrp5, Runx2, and TGFβ in EO771 tumor cells." (PMID 34830748, 2021). "The HSP90AB1 was significantly highly expressed in tumor tissues than normal tissues." (PMID 27756247, 2016). "Taken together, the result supported the anti-tumor action of extracellular Hsp90ab1, and not Hsp90aa1, in regulating Lrp5, Runx2, TGFβ, and IL27 in tumor cells." (PMID 34830748, 2021). "The results showed that the expression of HSP90AA1, HSP90AB1, and TRAP1 was positively correlated to the tumor purity, while that of HSP90B1 was not." (PMID 33145341, 2020). "Although no specific tumour-related gene was shared among the three groups, NOTCH2 was shared between BTG and PTCb while AR, HSP90AB1 and GNAS were shared between BTG and PTCa suggesting their possible roles in the BTG-to-PTCb and BTG-to-PTCa transformation, respectively." (PMID 36686473, 2022).
infection (23 papers, 2013 to 2025). The state of being infected such as from the introduction of a foreign agent such as serum, vaccine, antigenic substance or organism. "Furthermore, we found that the interaction of HSP90ab1 with CP was conserved across fish species which were susceptible to NNV, indicating HSP90ab1 might play important roles in RGNNV infection." (PMID 32639977, 2020). "Among the HSP90 gene family members, with the exception of hsp90ab1 and hsp90b1, which displayed an increasing trend at the onset of infection, the remaining members showed a significant decreasing trend following I. multifiliis infection." (PMID 39596645, 2024). "Members of the heat shock protein family such as HSP90AA1 and HSP90AB1 may support viral replication by modulating protein folding and stability during infection." (PMID 41404797, 2025). "Our latest study showed that infection with PRRSV induced a significant increase in the expression of HSPA8 and HSP90AB1, while matrine treatment could significantly reverse it, and the number of PRRSV viruses also decreased." (PMID 37511286, 2023). "We confirmed the translational regulation for HSP90AB1, one of the genes identified in cluster 5, by showing that protein amounts increase throughout infection while no significant changes in mRNA as measured by real-time PCR are observed." (PMID 26599541, 2015). "According to our analysis above, the difference between YN13 and YN144 in replication ability might be due to the difference between the two PEDV-infection groups in alterations of eIF4G1, hnRNPA1, HSP90B1, HSP90AB1, HSPA8, DNAJA1, and DNAJC10 in jejunums of pigs." (PMID 27916855, 2016). "Notably, hsp90ab1 showed an upward trend in the later stages of infection, a trend also found in Solea senegalensis infected with Photobacterium damselae, suggesting that expression changes in HSP90 gene family members may manifest only in the later stages of infection." (PMID 39596645, 2024). "Validation of the gene expression levels obtained by RNA-seq specific to the HCV group (BIRC5 and SLC22A1), the HBV group (CLEC1B), and the group without infection (FGFR4, HSF1, RNF187, HSP90AB1, and HSPB1) was performed using the real-time PCR technique." (PMID 36557005, 2022).
metabolic disease (4 papers, 2018 to 2025). A congenital disorder (due to inherited enzyme abnormality) or acquired (due to failure of a metabolically important organ) disorder resulting from an abnormal metabolic process. "In the present study, the HSP90ab1 isoform was demonstrated to be a contributor to the pathophysiology of metabolic disease." (PMID 29434648, 2018).
HSP90AB1 also shares sentences with these, for which no sentence is quoted: hepatocellular carcinoma (10 papers); Alzheimer disease (4); head and neck squamous cell carcinoma (4); nonalcoholic fatty liver disease (4); oral cancer (4); Hepatic steatosis (3); type 2 diabetes (3); adrenocortical adenoma (2); autoimmune disease (2); B-cell lymphoma (2); cardiovascular disease (2); cervical cancer (2); colorectal adenocarcinoma (2); idiopathic pulmonary fibrosis (2); interstitial lung disease (2); lung squamous cell carcinoma (2); multiple sclerosis (2); rectal cancer (2); stomach cancer (2); acute promyelocytic leukemia (1); adenocarcinoma (1); adenolymphoma (1); adenoma (1); adrenal cortex carcinoma (1); adrenocortical tumors (1); alcohol dependence (1); alopecia (1); amyloid (1); benign tumor (1); Burkitt lymphoma (1).
A further 72 diseases each share a sentence with HSP90AB1 in 1 paper.